TNF (tumor necrosis factor)
Diseases named in the same sentence as TNF in open-access papers (continued):
Sharing a sentence is not in itself a finding about the gene and the disease.
myocardial infarction (continued). "Treatment with curcumin showed a reduction in the levels of inflammatory mediators, such as IL-6, IL-1β, and TNF-α, in the myocardium in diabetic mice with myocardial infarction." (PMID 38338960, 2024). "TNF-α, as part of the early inflammatory phase, plays a significant role in the immune response following myocardial infarction 26,27." (PMID 38914598, 2024). "Asperosaponin VI, extracted from Dipsaci Radix, decreased the levels of TNF-α and IL-6 in myocardial infarction rats and collagen induced arthritis rats." (PMID 38974041, 2024). "In this study, we investigated the impact of TNF-α stimulation on BMSCs in enhancing therapeutic potential of exosomes derived from these cells for myocardial infarction repair." (PMID 38766777, 2024). "Increased TNF-α levels following acute myocardial infarction (AMI) contribute to impaired recovery of myocardial function." (PMID 38743187, 2024). "The TNF pathway is crucial in mediating the inflammatory response and affecting vascular function after myocardial infarction." (PMID 39717847, 2024). "An animal experiment showed that inhibition of the expression of TNF reduced the occurrence of AF after myocardial infarction." (PMID 38178669, 2024). "Typical cardiac biomarkers consisting of CRP, TNFα, CA-125, cTnI, cTnT, myoglobin, and CK-MB have an important role in diagnosing myocardial infarction (AMI)." (PMID 36832048, 2023). "The high burst of keywords, “myocardial infarction”, “vascular disease”, “coronary artery disease”, and “TNF-α”, suggest that these areas have undergone extensive research and received a high level of attention over a specific time period." (PMID 36837593, 2023). "Studies have shown that in acute myocardial infarction, myocardial cells secrete exosomes rich in tumor necrosis factor, which leads to myocardial cell damage." (PMID 36818340, 2023). "Inflammatory cytokines, such as IL-1, IL-6, and TNF-α, have been shown to increase dramatically after myocardial infarction and are involved in future LV remodeling." (PMID 35538296, 2023). "One of the key mechanisms by which TNF contributes to myocardial infarction is through the induction of oxidative stress." (PMID 36984421, 2023). "Compared with the model group, Rb1 reduced myocardial infarction size, and caspase-3 activity, TNF-α levels, and phosphorylated p38 MAPK levels were also reduced by Rb1 pretreatment (Li and Ji, 2018)." (PMID 37547332, 2023). "A recent meta-analysis showed that the TNF-α and IL-1 family were involved in plaque formation and, consequently, in the incidences of myocardial infarction." (PMID 36324755, 2022). "TNF-α is a proinflammatory cytokine elevated in the early phase of wound healing after myocardial infarction as well as in progression of ischemic heart failure and is associated with advancing fibrosis." (PMID 34854055, 2022). "After myocardial infarction, a large amount of TNF-α is produced by ischemia and hypoxia-activated cardiomyocytes and local mononuclear macrophages." (PMID 36060429, 2022). "For example, in a myocardial infarction rat model, L. angustifolia EO significantly reduced TNF-α and COX-2 expression by inhibiting NF-кB activity." (PMID 36474235, 2022). "In heart illnesses such dilated cardiomyopathy, myocardial infarction, and left ventricular pressure overload, circulating and cardiac TNF- levels are high." (PMID 35781619, 2022). "Although the significant increase in IL-6 was lost at follow-up, TNF-α levels remained significantly increased 1 year after myocardial infarction." (PMID 35681518, 2022). "Recent evidence suggests indeed that circulating MVs from myocardial infarction patients are primed toward a cardioprotective potential upon TNFα-induced cell damage." (PMID 35563201, 2022). "As a potential treatment for myocardial infarction, they employed gold nanoparticles (AuNPs) functionalized with deoxyribozyme (DNAzyme) to catalytically quiet tumor necrosis factor (TNF) in vivo." (PMID 36684578, 2022).
myocardial infarction (continued). "Several authors have shown that ISO-induced myocardial infarction was accompanied by an increase in inflammation mediators like interleukin-1, interleukin-6, and tumor necrosis factor-alpha, which would be responsible for cardiac edema." (PMID 35186101, 2022). "We found that exosomes from myocardial infarction patients with a low level of miR-146a-5p promote macrophage polarization but induce an increase of TNFα and iNOS expression." (PMID 35548775, 2022). "We also find that CCN5 transcription is repressed by TNF-α, an inflammatory mediator highly elevated in early phases of wound healing following myocardial infarction." (PMID 34854055, 2022). "Emerging studies have identified that immune cells infiltrate myocardial tissue during myocardial infarction and release a large number of pro-inflammatory cells, including IL-1β, IL-6, IL-17A and TNF-α." (PMID 36483733, 2022). "The expression of inflammatory factors, including tumor necrosis factor-α (TNF-α) and interleukin (IL)-1β, significantly increases after myocardial infarction (MI) in rats and has important roles in the etiology of ventricular remodeling." (PMID 35928246, 2022). "During myocardial infarction, various pro-inflammatory cytokines including TNFα, IL-6, IL-1β, and TGF-β1 are released, promoting cardiac remodeling." (PMID 35883637, 2022). "It was further demonstrated that YQFM reduced the size of myocardial infarction, improved cardiac function, and inhibited the expression of inflammatory cytokines, such as tumor necrosis factor-alpha (TNF-α), NF-κB, IL-6, and interleukin-1β (IL-1β)." (PMID 36506553, 2022). "Administration of FGF21 decreased the mRNA expression of interleukin-6 (IL-6) and tumor necrosis factor-α (TNF-α) and protected against pathological myocardial remodeling and improved cardiac function at 2 weeks in a myocardial infarction mouse model." (PMID 36440004, 2022). "The pro-inflammatory cytokines released in response to myocardial infarction include IL-1α, IL-1β, IL-6, TNFα, IL-8, IL-18 and small chemokine molecules such as monocyte chemoattractant protein 1 (MCP-1)." (PMID 33629195, 2021). "DAP revealed efficient ameliorative actions against ISO-caused MI by marked reduction in myocardial infarct size and suppressed oxidative stress, inflammation, and apoptosis via the up-regulation of the Nrf2/HO-1; TLR4/TNF-α signaling pathways." (PMID 34093197, 2021). "NF-κB is a multiple transcription factor that regulates transcription of various genes involved in the pathogenesis of myocardial infarction like TNF-α and IL-6." (PMID 34266475, 2021). "NF-κB is implicated in the expression of many downstream proinflammatory genes, such as Cox-2, TNF-α, IL-1β, and IL-6, which are involved in the inflammation response in myocardial infarction and myocardial ischemia/reperfusion." (PMID 34304702, 2021). "The odds of having a heart attack were eight times higher in the presence of elevated triglycerides and pro-inflammatory markers (TNFα and IL6) as compared to presence of pro-inflammatory markers only." (PMID 33510184, 2021). "The cytokine response to infection is similar in the acute phase to myocardial infarction, and is triggered by DAMPS and danger signals following pathogenic invasion (stimulating IL-6, TNFα and IL-1β)." (PMID 33629195, 2021). "Further, the odds of heart attack increased up to 15 times for participants with elevated levels of TNFα in presence of high triglyceride expression." (PMID 33510184, 2021). "Several studies have described an increased expression of proinflammatory cytokines IL-1β, IL-6, and TNF-α in ISO-induced myocardial infarction." (PMID 34072098, 2021). "The down‐regulation of TNF‐α, IL‐1β and IL‐6 has been found to exert an anti‐inflammatory effect on the development of myocardial infarction." (PMID 32783282, 2020).
myocardial infarction (continued). "Inhibiting TNF-α through gene therapy to express the soluble TNF receptor produced deleterious effects in a mouse model of myocardial infarction through increased incidence of cardiac rupture and augmented cardiac remodeling." (PMID 33041853, 2020). "In our results, after knockdown RXFP1 by specific RXFP1 siRNA, mast cell markers chymase and tryptase, inflammatory cytokines IL-6 and TNF-α, and classic phosphorylated NF-κB all increased, which was consistent with the acute myocardial infarction outcomes." (PMID 32859236, 2020). "This is likely of importance in humans as TNF levels post-myocardial infarction are a strong predictor of recurrent events." (PMID 32805626, 2020). "MiR-375 regulates the expression of pro-inflammatory cytokines such as IL1-β, TNFα, and IL-6: therefore, miR-375 decrease also reduces cytokine expression, as shown in a myocardial infarction model." (PMID 32547539, 2020). "Increased levels of TNF-α were the predictions of sudden coronary death and cardiovascular events after acute myocardial infarction." (PMID 33029103, 2020). "There is one retrospective cohort study including 8845 psoriatic patients that compares the effects of TNF-α inhibitors, oral agents or phototherapy, and topical therapy on the incidence of myocardial infarction (MI)." (PMID 33262910, 2020). "Lots of inflammatory cytokines, such as tumor necrosis factor alpha (TNFα) and various chemokines that are weakly represented in healthy hearts, reach high levels during myocardial infarction." (PMID 33143256, 2020). "In a surgical ligation mouse model of myocardial infarction, it was recently shown that iRhom2-mediated TNF signaling is involved in tissue repair and wound healing in the myocardium following myocardial infarction." (PMID 33330676, 2020). "Levels of tumor necrosis factor alpha (TNF-α) also declined considerably in the serums of rats with myocardial infarction." (PMID 32599693, 2020). "The results indicate that the level of TNF-α was considerably increased in animals with myocardial infarction compare to the control group." (PMID 32211137, 2020). "In the rat model of acute myocardial infarction, quercetin administration determined the reduction of TNF-α, IL-1β expression in the myocardial tissue, in parallel with an increase of the antioxidant SOD and catalase activities." (PMID 32326376, 2020). "Our previous data indicate that the serum or plasma levels of TNF-α are significantly higher in the patients with BP or acute myocardial infarction to that of controls." (PMID 31001258, 2019). "In the present study, myocardial infarction increased the TNF-α and IL-6 levels in normotensive and L-NAME-induced hypertensive rats." (PMID 31052164, 2019). "TNF-α and IL-6 are proinflammatory cytokines involved in the synthesis of collagen and scar formation after acute myocardial infarction." (PMID 31205590, 2019). "Post-myocardial infarction patients have increased circulating mDNA levels, accompanied by higher levels of inflammatory cytokines, such as TNF-α and IL-6, compared to healthy individuals." (PMID 32009974, 2019). "In the current study, we found that 10 weeks after myocardial infarction in rats, levels of serum IL-6 and TNF-α were significantly increased." (PMID 30789913, 2019). "RK was previously reported to reduce hepatic TNF-α and inflammation in non-alcoholic steatohepatitis and in isoprenaline-induced myocardial infarction." (PMID 31404064, 2019). "TNF-α and IL-6 were increased by 125% and 79% respectively, after myocardial infarction in the normotensive group (WKY + MI) vs. WKY + sham group (p < 0.01)." (PMID 31052164, 2019). "The protein reduces apoptosis of cultured cardiomyocytes subjected to hypoxia and tumour necrosis factor-alpha (TNF-α) and prevents the injury of cardiac muscle cells in mice after myocardial infarction (MI)." (PMID 30482253, 2018).
myocardial infarction (continued). "Previous work showed that MSCs transduced with the TNF receptor gene showed improved survival and ventricular function after transplantation at an acute myocardial infarction site due to attenuated TNF-α levels in the serum and cardiac tissue." (PMID 30409167, 2018). "TNFα levels are increased after acute myocardial infarction and induce acute inflammatory responses, including vascular insulin resistance." (PMID 29464018, 2018). "In patients with acute myocardial infarction, TNF-α antagonist etanercept was used in one trial with 26 patients." (PMID 28460644, 2017). "One study indicated that the upregulation of myocardial pro-inflammatory genes (TNF-alpha, IL-1beta and IL-6) and coronary thrombosis in rats with myocardial infarct induced by isoproterenol were both stopped by zingerone pre-treatment." (PMID 29206854, 2017). "Levels of TNF-α and its receptors are elevated also in patients with acute myocardial infarction and can predict infarct size, LV dysfunction and prognosis." (PMID 28460644, 2017). "Since TNF-α is involved in IHD pathological pathway, TNF-α gene polymorphisms and their association with the risk of myocardial infarction and coronary artery disease (CAD) have been extensively studied." (PMID 28460644, 2017). "Myocardial infarction in the I group significantly increased the concentrations of all the inflammatory cytokines analyzed, including IL-1β, IL-6 and TNF-α, as well as anti-inflammatory cytokine IL-10." (PMID 29057895, 2017). "It has been reported that the activation of pro-inflammatory cytokines such as TNF-α has an important role in worsening ischemic injury following myocardial infarction." (PMID 27874107, 2017). "Myocardial infarct sizes, histological scores, levels of circulating and myocardial IL-6 and TNF-α, the expression of HMGB1, TLR4, MyD88 and NF-κB, and the degradation of IκB were significantly increased in the I/R group compared with the sham group (P<0.01)." (PMID 28222157, 2017). "In an in vivo murine model of myocardial infarction, TNF-α showed its cardiotoxic effect through receptor TNFR1 and cardioprotective effect through TNFR2." (PMID 28460644, 2017). "SI1 exhibited higher levels of TNF-α than EI1 did at in the myocardial infarct and the myocardium distant from the infarct (both p<0.05)." (PMID 27074178, 2016). "Macrophage is a major cellular component of inflammatory reaction in myocardial infarction, generating pro-inflammatory cytokines such as IL-1, IL-6 and TNF-α that play central roles in the initiation and maintenance of inflammation." (PMID 26882996, 2016). "Proximal inflammatory cytokines such as tumor necrosis factor alpha (TNFa) and variety of chemokines are scant in healthy hearts, however their levels spike up during myocardial infarct." (PMID 27069565, 2016). "After myocardial infarction (MI), TNF-α is locally released from ischemic cardiomyocytes and remains markedly elevated in advanced HF10." (PMID 26659007, 2015). "Administration of SHED-CM reduced myocardial infarct size as well as decreased apoptosis and inflammatory cytokine levels, such as TNF-α, IL-6, and IL-β, in the myocardium following I/R." (PMID 26542315, 2015). "To disentangle the association of IL6R with inflammation and risk of CHD, we analyzed the association of IL6R haplotypes with circulating levels of inflammatory biomarkers [CRP, fibrinogen, sIL6R, IL6, interleukin 8 (IL8) and TNF-α] and with the risk of myocardial infarction (MI) and CHD." (PMID 25781951, 2015). "Our previous study demonstrated that the involvement of the JAK/STAT signaling pathway in the occurrence and development of myocardial infarction is closely correlated with its promotion on NF-κB activation and TNFα expression." (PMID 25329324, 2014). "In in vivo rat model of myocardial ischemia/reperfusion injury, we found that treatments with citric acid and L-malic acid significantly reduced myocardial infarct size, serum levels of TNF-α, and platelet aggregation." (PMID 23737849, 2013).
myocardial infarction (continued). "This study determines the roles of tumor necrosis factor-α (TNFα) and lymphotoxin-α (LTα) in post-myocardial infarction (post-MI) cardiac injury, and identifies the TNF receptor type responsible for TNFα- and LTα-mediated cardiac injury." (PMID 23704873, 2013). "Using the Kaiser Permanente healthcare database in California, a retrospective cohort study of 24,081 psoriasis and PsA patients examined the effect of TNF-α inhibitors on the incidence of myocardial infarction." (PMID 23209897, 2012). "Elevated plasma levels of IL6 and TNFα were detected in patients with stable or unstable angina and myocardial infarction." (PMID 22883023, 2012). "It has been demonstrated that inflammatory cytokines, including IL-1β, IL-6, and TNF-α, increase remarkably after myocardial infarction and are involved in the subsequent left ventricular remodeling." (PMID 22792312, 2012). "The purpose of this study was to explore the effects of tumor necrosis factor-α (TNF-α) on ventricular fibrillation (VF) in rats with acute myocardial infarction (AMI)." (PMID 21584281, 2011). "More interestingly, 6 months after myocardial infarction, in the same group of patients, TNFα production was persistently higher than that in the patients not undergoing left ventricular remodeling." (PMID 20467464, 2010). "The changes correlated with the amount of damage and disease outcome, and the systemic elevation in TNF-α served as an independent determinant of reperfusion injury after acute myocardial infarction." (PMID 19421412, 2009). "The present study is established that bone marrow cells were effective for inducing therapeutic angiogenesis in a rat acute myocardial infarction model, the mechanism of which related to an increase in inflammatory cytokines, such as IL-1β, TNF-α and sVCAM." (PMID 18492279, 2008). "Notably, a recent study published in JAHA identified TNF-α as a key mediator of myocardial infarction; infliximab infusion in an experimental porcine model led to reduced myocardial injury and improved cardiac recovery." (PMID 41155452, 2025). "In contrast, VEGFA (0.919; 0.847–0.998; P = 0.044), KIT (0.754; 0.575–0.988; P = 0.041), TNF (0.881; 0.796–0.974; P = 0.014), CTNNB1 (0.920; 0.858–0.986; P = 0.018), and GGT1 (0.887; 0.796–0.989; P = 0.030) were associated with lower risk of myocardial infarction." (PMID 41573742, 2025). "In addition, administration of L-carnitine in animal with myocardial infarction shows effects in reducing oxidative stress and enhancing antioxidant enzyme activity through the inhibition of TNF-α and IL-1β." (PMID 39283525, 2025). "Moreover, TNF-α is regulated by miR-21 and has a crucial role in the occurrence of acute myocardial infarction in the elderly." (PMID 38699693, 2024). "The results showed that resveratrol could reduce ST segment, cTn-I, cTn-T, CK, CK-MB, LDH, LVEDP, ROS, MDA, TNF-α, IL-6, AI levels and myocardial infarction size." (PMID 38313308, 2024). "Furthermore, inflammatory cytokines, such as interleukin-1, monocyte chemoattractant protein-1, and tumor necrosis factor-α are known to be elevated in the acute phase of myocardial infarction." (PMID 38355442, 2024). "TNF-alpha promoter genetic variations have been linked to TNF-alpha serum concentrations, which have been linked to first-time coronary heart disease and are a biomarker for repetitive cardiovascular events following a previous myocardial infarction." (PMID 36622512, 2023). "Furthermore, HU308 (IP 2 mg/kg) has been shown to be successful in the prevention of myocardial infarction damage by reducing inflammatory markers such as IL-1β and TNF-α." (PMID 37631062, 2023). "Administration of taurine (100 mM) in Wistar rats 30 days after coronary artery occlusion-induced ischemia significantly decreased myocardial infarct size and reduced expression of IL-6 and TNF-α, suggesting that taurine provides anti-inflammatory cardio-protective effects." (PMID 37299525, 2023).